BRAF (B-Raf proto-oncogene, serine/threonine kinase)
Diseases named in the same sentence as BRAF in open-access papers (continued):
Sharing a sentence is not in itself a finding about the gene and the disease.
melanoma (continued). "BRAF-inhibitor-induced TGF-β release in melanoma cells has been demonstrated to promote the activation of CAFs." (PMID 37370757, 2023). "EVs transporting active ALKRES from vemurafenib-resistant melanoma cells to recipient cells sensitive to this drug were capable to re-activate the BRAF/MEK/ERK pathway in drug-treated sensitive cells." (PMID 36674479, 2023). "For instance, BRAF inhibitors plus MEK inhibitors treatment can activate GSDME pyroptosis to enhance anti-tumor immunity in GSDME-expressing melanoma." (PMID 36742298, 2023). "In BRAF mutant melanoma cells (A375 and SK-MEL-28), the activation of p38 MAPK is associated with the negative regulation of subtype 4b plasma membrane Ca2+ pumps (PMCA4b), a metastasis suppressor." (PMID 38004419, 2023). "For this study, stage III BRAF V600 mutant cutaneous melanoma patients treated with adjuvant BRAF/MEK-inhibition or anti-PD-1 were identified from the Dutch Melanoma Treatment Registry." (PMID 36672358, 2023). "In particular, BRAF mutations and MAPK hyperactivation induce melanoma cell proliferation, mitochondrial alterations and drive metabolism switching from OXPHOS to glycolysis and support high metabolic flexibility." (PMID 37160873, 2023). "Because we planned to use apoptosis as readout of the treatment efficacy, apoptosis induction was examined in response to treatment of melanoma cells with the BRAF inhibitor PLX4032 as well as to conventional antitumor agents such as cDDP and TMZ." (PMID 37790750, 2023). "A downregulation of miR-7, miR-579 3p, and miR-126 3p was found in melanomas resistant to BRAF/MAPK inhibitors, while miR-31 downregulation is associated with chemoresistance." (PMID 37958863, 2023). "In recent years, treatment efficacy in patients with melanoma has been improved by the use of targeted therapies, such as BRAF, CTLA4, and PD1 inhibitors." (PMID 37886980, 2023). "Ascierto and colleagues demonstrated that patients (stage IIC to IIIC) with BRAFV600E/K melanoma and low TILs had a greater benefit in terms of disease-free survival after adjuvant BRAF inhibition (vemurafenib) compared to those with high TILs." (PMID 37295047, 2023). "In melanoma patients, AR signaling induction highly impairs efficacy of BRAF/MEK targeted therapy, which provides the explanation of why female patients display significantly higher response rates." (PMID 37434223, 2023). "The brain is a frequent site of recurrence in BRAF-mutant melanoma patients across different ethnicities." (PMID 37568570, 2023). "BRAF mutant melanoma cell lines resistant to the BRAFV600E inhibitor PLX4720 have been shown to upregulate WNT5A, and their sensitivity was restored by WNT5A depletion." (PMID 36539575, 2023). "Third, BRAF mutant melanoma cells generate cell subclones, dubbed persisters, that are resistant to clinical drug targeting of this kinase." (PMID 37762668, 2023). "After BRAF mutations, NRAS mutations are the second most common oncogenic driver genetic mutations in melanoma." (PMID 36600247, 2023). "BRAF-mutant colorectal cancer is more prone to acquired resistance than BRAF-mutant melanoma, although CRAF was activated by oncogenic EGFR signaling in the former." (PMID 38111008, 2023). "Melanomas that arise on sites with intermittent UVR exposure are more frequently of SSM type, more likely to harbour a BRAF V600E mutation and arise from a pre-existing nevus." (PMID 36765773, 2023). "Depleting PDK1 also led to the regression of established melanomas and eliminated melanoma subpopulations that were resistant to targeted BRAF inhibition." (PMID 37649668, 2023). "In melanomas, the clinically approved BRAF inhibitor vemurafenib has been reported to induce T-cell antigen expression and stimulate a T-cell immune response." (PMID 37631380, 2023). "BRAF inhibitors interfere with the mitogen-activated protein kinase (MAPK) signalling pathway that regulates melanoma proliferation and survival." (PMID 37205232, 2023).
melanoma (continued). "Treatment of melanoma in 2019 was represented by two therapeutic groups (99.86% of expenditure), including the combination of BRAF serine-threonine kinase inhibitors and MEK kinases (53.17%) and immune checkpoint inhibitors (46.69%)." (PMID 37754495, 2023). "Higher percentages of BRAF, RAS, NF1, and CBL mutations were observed in patients with melanoma in the head and neck than in patients with melanoma in the other five sites." (PMID 37649078, 2023). "In contrast, other studies were able to prove the role of ER stress in the induction of apoptosis by BRAF inhibitors as a strategy to similarly treat NRAS-mutant melanoma." (PMID 38067230, 2023). "To investigate cell-type specificity of functionally enriched enhancers, we performed CRISPRi screening on a BRAF wild-type melanoma cell line, SK-MEL-2." (PMID 37904237, 2023). "There is also a study indicating that microphthalmia-associated transcription factor (MITF) inhibitor CH6868398 sensitized melanoma cells to BRAF kinase inhibitor." (PMID 36834830, 2023). "BRAFV600 mutational status was examined in 104 patients (77.0%); the number of patients with BRAF wild‐type and BRAF mutant melanoma was 50 (37.0%) and 54 (40.0%), respectively." (PMID 38083908, 2023). "Collectively, our study supported the oncogenic functions of TCF12 in melanoma, revealing it as a potential target to improve the efficacy of BRAF(V600E)-targeted therapy." (PMID 37760480, 2023). "A high level of nectin-4 was significantly associated with BRAF mutation and worse DFS, melanoma-specific survival and OS, and therefore also indicated poor prognosis." (PMID 37568798, 2023). "In the murine melanoma model, induction of pyroptosis using a nano-gel consisting of a BRAF inhibitor and a COX2 inhibitor resulted in a significant increase in the populations of CD80+ CD86+ DCs and CD3+ CD8+ T cells within the tumor." (PMID 37373523, 2023). "This is the first study to report on the molecular mechanism of action of M. cochinchinensis seed extracts on BRAF mutant melanoma cells." (PMID 36678596, 2023). "For example, tumors induced by xenotransplantation of a melanoma cell line first shrank upon treatment with the BRAF inhibitor vemurafenib, but after only 10 days regained growth." (PMID 37174007, 2023). "We next wanted to determine what inherent processes within chronic treated BRAF-inhibitor resistant melanoma cells were affected by HMGCR-inhibitor treatment." (PMID 37277330, 2023). "A perioperative combination of encorafenib plus binimetinib will be compared to standard adjuvant therapy in the phase II PREMIUM trial in BRAF V600E mutant patients in stage III (B/C/D) or oligometastatic resectable stage IV melanoma (NCT05097378)." (PMID 37888038, 2023). "Nevertheless, this system allows rapid comparison of multiple conditions, and works with small samples such as human BRAF-V600E melanoma biopsies." (PMID 38164473, 2023). "In our cohort of BRAF-mutated melanoma patients, we showed that TERT promoter mutation status and TERT expression tended to be associated with the response to BRAF and MEK inhibitors." (PMID 37296851, 2023). "RIPK4 kinase has oncogenic functions in melanoma and shows high similarity to BRAF protein, making this kinase sensitive to the BRAF inhibitors vemurafenib and dabrafenib." (PMID 36765875, 2023). "Melanoma cell lines with single resistance to Vemurafenib (BRAF inhibitor) and double resistance to Vemurafenib/Selumetinib (MEK inhibitor)exhibit increased glutamine uptake and NH4+ production without changes in glucose uptake." (PMID 36959802, 2023). "Cutaneous melanoma was the primary in 270 patients (84.9%), 171 (53.8%) had BRAF/NRAS wild-type variants, 113 (35.5%) had resected stage IIIB, and 124 (39.0%) had resected stage IIIC melanomas (AJCC Cancer Staging Manual, version 8)." (PMID 37535354, 2023). "In this cohort, 45 patients received a combination of BRAF and MEK inhibitors for metastatic BRAF-mutated melanoma." (PMID 37296851, 2023).
melanoma (continued). "We used the BRAF V600E mutant M238 melanoma cell line from our test panel since it is highly sensitive to growth inhibition." (PMID 37803324, 2023). "Class 2 vs 3 variants are noted in melanoma (11.3% vs 9.4%), CRC (5.6% vs 15.2%), and NSCLC (20.8% vs 19.1%), which commonly carry BRAF variants." (PMID 36867406, 2023). "To accomplish this, we treated Yale University Mouse Melanoma (YUMM) lines with the BRAF inhibitor, Vem, in vitro to generate resistant cells." (PMID 37762086, 2023). "Activated MAFs are sufficient to produce denser collagen fibrils in the ECM and drive drug resistance to PLX4032 in BRAF-mutant melanoma cells." (PMID 37569866, 2023). "Targeted therapy with BRAF‐ and MEK‐Inhibitors (BRAFi, MEKi) provides an excellent therapeutic option for patients with malignant melanomas with a BRAF‐Mutation." (PMID 36751314, 2023). "To model this clinical paradigm in vitro, we assessed five BRAF(V600E)-mutant melanoma cell lines with high PGC1α expression at baseline and subjected them to chronic treatment with the BRAF inhibitor PLX403216." (PMID 37277330, 2023). "Class 3 BRAF mutations and NF1 loss were common in various HRAS-mutant cancers, in particular melanomas." (PMID 37503077, 2023). "Elevated expression of TPL2 in BRAF V600E‐mutated melanoma cells is known to confer resistance to BRAF inhibitors, and TPL2 expression is higher in patients with relapse after BRAF inhibitor therapy." (PMID 36847709, 2023). "The JUN family TFs and ETV5 are essential regulators of CDK6, which together mediate resistance to BRAF inhibitors in melanoma cells." (PMID 36872348, 2023). "To test the sensitivity of Pex3+/– melanomas to BRAF inhibition in vivo, we next injected D4M.3a Cas9-Ctrl, Pex3+/– clone 6D, or Pex3+/– clone 9G cells into syngeneic mice." (PMID 37616051, 2023). "For example, the combined use of BRAF and MEK inhibitors was applied in the treatment of patients with advanced BRAF-mutated melanoma." (PMID 37446286, 2023). "Clinically, union application of BRAF and MEK1/2 inhibitors was the first-line therapy in BRAF V600E mutant advanced melanoma patients." (PMID 36872366, 2023). "In melanomas, the somatic BRAF mutation rate is the highest among cancer types and pathogenetic variants in the BRAF (OMIM*164757) gene occur in about 50% of melanoma-affected patients." (PMID 37627054, 2023). "Our findings demonstrate that 3a is an important antitumor candidate prototype and support further investigations to evaluate its potential for melanoma treatment, especially for refractory cases to BRAF/MEK inhibitors." (PMID 37259298, 2023). "Tumors from animals were more invasive and had higher RAS/MAPK pathway activation, while KIT knockdown increased RAS/MAPK pathway activation in a BRAF‐mutant human melanoma cell line." (PMID 37506147, 2023). "For example, during the development of resistance to BRAF inhibition in melanoma, the MAP kinase pathway was re-activated via several different routes such as RAS mutations, mutant BRAF amplification and alternative splicing." (PMID 37721639, 2023). "In BRAF-mutant melanoma, BRAF inhibitors (PLX4032) remarkably can remodel surrounding ECM by activating melanoma-associated fibroblasts (MAFs) through phosphorylation of MLC2/MYL9, which is the key regulator of actomyosin contractility." (PMID 37569866, 2023). "BRAF inhibitors, such as vemurafenib and dabrafenib, have been approved for the treatment of BRAF-mutant melanoma, showing significant clinical benefits." (PMID 37446128, 2023). "Of note, the AHR/SRC axis has recently been discovered as a new therapeutic vulnerability that triggers resistance to BRAF (B-Raf proto-oncogene, serine/threonine kinase) inhibitors in melanoma." (PMID 37696456, 2023). "HA-15 triggered apoptosis and induced autophagy in melanoma cells and prevented the growth of melanoma cells including those resistant to BRAF inhibitors in a mouse xenograft model." (PMID 37189349, 2023).
melanoma (continued). "His history was significant for resected stage IIIB melanoma (BRAF wildtype), hypertension, dyslipidaemia, non-alcoholic fatty liver disease and obesity for which he took perindopril and amlodipine." (PMID 36895912, 2023). "The genetic makeup of the triple-wild-type melanoma (BRAF, NRAS and NF1) has been known for some time, but those studies grouped together rare histopathological versions with common ones, as well as mucosal and even uveal ones." (PMID 36980598, 2023). "In line with our results, the authors demonstrated a preference for TT in stage III BRAF-mutant melanoma patients with autoimmune diseases (76.5% versus 23.5%, p = 0.02)." (PMID 36672358, 2023). "According to multiple studies, RAF/RAS isoforms activate the Nrf2 pathway, and BRAF/NRAS mutant melanomas express more Nrf2." (PMID 36747120, 2023). "Targeted therapies against BRAF (vemurafenib, dabrafenib, and encorafenib) are currently available and widely used in advanced melanomas and recurrent or metastatic thyroid carcinomas." (PMID 37999148, 2023). "Vemurafenib, dabrafenib, and encorafenib, known as BRAF inhibitors, are employed in the treatment of patients afflicted with BRAF-mutant melanoma." (PMID 38021761, 2023). "Patients with BRAF-mutant melanoma have shown improved response rates and progression-free survival when treated with targeted therapies." (PMID 38202898, 2023). "In the context of BRAF mutant melanoma, here, we demonstrate the applicability of a lipid metabolic additive therapy combination that exploits acquired vulnerabilities in augmenting a therapy response." (PMID 37072838, 2023). "Molecular testing for common melanoma driver genes, including BRAF, NRAS, KRAS, HRAS, NF1, and KIT, was available for this study." (PMID 37686691, 2023). "The observed treatment failure in melanoma patients was found to result from BRAF/MEK-inhibitor-induced activation of the SEMA6A/RhoA/YAP axis as consequence of the crosstalk between tumor and stromal cells." (PMID 37370757, 2023). "In the case of melanoma, mutations in another RAS gene, NRAS, have been reported as one of the resistance mechanisms to BRAF inhibition." (PMID 36967525, 2023). "When tested in the A375 human melanoma cell line, we observed a similar reduction in viral infection with BRAF/MEK inhibitors." (PMID 38201278, 2023). "Since 2011, however, the rules of stage IV melanoma treatment have been completely rewritten, with the introduction of Targeted Therapies (TTs) with BRAF and MEK inhibitors (BRAF+MEKi), and of immunotherapy with anti CTLA-4 and anti-PD-1." (PMID 36901733, 2023). "For example, BRAF inhibition alone using vemurafenib demonstrated striking lack of efficacy in colorectal cancer patients, in contrast to BRAFmut melanomas, and produced a response rate of only 5%." (PMID 37791907, 2023). "Long-term efficacy data of combination nivolumab plus ipilimumab in the BRAF-mutant melanoma subgroup in the CheckMate 067 study are of much interest." (PMID 37404764, 2023). "In melanoma, there are mounting data that oncogenic BRAF contributes to immune escape, and several clinical trials combined BRAF inhibitors with immune checkpoint blockade." (PMID 36673047, 2023). "Ganetespib was more effective than single-agent vemurafenib in melanoma cell lines driven by mutant v-raf murine sarcoma viral oncogene homolog B1 (BRAF), because this protein is a very sensitive HSP90 client." (PMID 36902446, 2023). "As such, prospective clinical trials have sought to compare therapeutic responses of ICI and TT as first‐ or second‐line treatments in BRAF‐mutant melanoma." (PMID 36967556, 2023). "Another study to have investigated the treatment sequence in patients with BRAF-mutant unresectable melanoma was DREAMseq." (PMID 37543586, 2023).
melanoma (continued). "In summary, our results show for the first time that the in vivo systemic delivery of LNPs encapsulating oncosuppressor miRNAs potentiate target therapies for BRAF-mutant melanomas and significantly delay the emergence of drug resistance." (PMID 36418472, 2023). "Acral melanomas harbor KIT, NRAS, and BRAF mutations, mucosal melanomas KIT and NRAS mutations, and uveal and melanomas arising in blue nevi uniquely have GNA11 and GNAQ mutations." (PMID 37841001, 2023). "We previously showed that mutant BRAF drives the overexpression of HMOX1, which, in turn, forces the nuclear localization of mutant BRAF and drives proliferation and metastasis in melanomas via reactivation or persistent activation of MAPK signaling." (PMID 37176114, 2023). "BRAF mutation is present in up to 8% of cancer cases; specific BRAF inhibitors such as dabrafenib and vemurafenib were approved for use in metastatic colon cancer and melanoma." (PMID 37849806, 2023). "This evolution-based approach to cancer treatment has been integrated into several ongoing or planned clinical trials, including treatment of metastatic castrate resistant prostate cancer, ovarian cancer, and BRAF-mutant melanoma." (PMID 36952376, 2023). "Although melanomas with RAF1 fusions are seldom observed (less than 1%), clinical sample analyses have consistently shown that melanomas harboring RAF1 fusions exhibit wide-type status for BRAF, RAS, and NF1." (PMID 38111008, 2023). "The coexistence of mutations in BRAF and NRAS genes as well as in TERT promoter are associated with poor disease-free survival in melanoma patients." (PMID 38033865, 2023). "Among our cohort of 36 patients, we analyzed 12 melanoma patients (4 BRAF V600+ and 8 BRAF V600−) for which matched pre-therapy and post-therapy biopsies were available, to identify potential genetic predictors of intrinsic and/or acquired resistance." (PMID 36901733, 2023). "Given the emerging clinical evidence for this practice, our systematic review and meta-analysis aims to investigate the efficacy and safety of rechallenging advanced BRAF-mutant melanoma patients with MAPK inhibitors." (PMID 37568570, 2023). "BRAF inhibitors-induced activation of CAFs has been shown to trigger both tumor progression and treatment resistance in melanoma cells." (PMID 37370757, 2023). "Benign melanocytic nevi harbour trunk nucleotide changes, such as BRAF and NRAS mutations, before progressing to melanoma and accumulate nucleotide changes in TERT promoter at the transition from benign nevus to melanoma in situ." (PMID 38033865, 2023). "Currently, the standard first-line treatments for advanced melanoma are the immune checkpoint inhibitors and BRAF+ MEK inhibitor combinations." (PMID 37664072, 2023). "With both Aurora and MEK inhibitory components, BI-847325 was shown to overcome acquired resistance to BRAF inhibitors in two-dimensional (2D) and three-dimensional in vitro settings and in in vivo models of melanoma." (PMID 37830744, 2023). "Gene expression analysis revealed that BRAF mutation elevated the mRNA level of Ref-1 in PTC (P < 0.0001), while melanoma exhibited the opposite pattern (P = 0.0115)." (PMID 35136031, 2022). "In a later study by the same group, it was shown that introducing oncogenic mutant BRAF V600E into human melanoma cells led to high levels of aberrant spindles, supernumerary centrosomes, and the mis-segregation of chromosomes." (PMID 36276131, 2022). "STAT3–PAX3 signaling is also involved in generating the resistance of melanoma cells to BRAF inhibitors." (PMID 35565444, 2022). "In the present study, we provide evidence of the involvement of SEMA6A in the biology of BRAF-mut melanoma and the premise for its possible use as a predictive biomarker." (PMID 35440004, 2022). "We apply this method to our zebrafish BRAF mutant melanoma models and demonstrate that the melanomas respond to vemurafenib drug-pellet therapy." (PMID 35394030, 2022).